CD4 (CD4 molecule)
Diseases named in the same sentence as CD4 in open-access papers (continued):
Sharing a sentence is not in itself a finding about the gene and the disease.
asthma (continued). "Immune infiltration analysis revealed significant differences in the proportions of memory CD4 + T cells and mast cells between high-risk and low-risk groups, suggesting that iron metabolism imbalance may contribute to asthma development via immune regulatory mechanisms." (PMID 41984875, 2026). "CD4+ T cells can further differentiate into T helper 1 (Th1) cells and T helper 2 (Th2) cells and participate in cellular and humoral immunity, and Th1/Th2 dysregulation is associated with various chronic inflammatory airway diseases such as asthma and chronic bronchitis." (PMID 40337271, 2025). "Although the exact mechanism driving the IL-17-dominated cellular environment in asthma is not fully understood, our study observed an increased expression of the transcription factor RORγt, a master regulator of Th17 cell differentiation, in CD4+ T cells in the asthmatic Nrf2-deficient mice." (PMID 39061887, 2024). "Memory-type pathogenic CD4+ Th2 cells may also contribute to steroid-resistance in T2-high asthma." (PMID 37296458, 2023). "Hence, one could hypothesize that patients with 17q12-21 asthma risk SNPs correlating with ORMDL3 overexpression may display increased Th2 CD4+ T-cells and associated cytokine profiles." (PMID 33424845, 2020). "In the end, we hypothesize that skewed CD4+ T cell differentiation in the context of elevated ORMDL3 likely culminates in chronic inflammation associated with heightened disease pathogenesis in asthma patients carrying the 17q12–21 risk SNPs." (PMID 33424845, 2020). "Asthma is classically considered an IgE-mediated, lymphocyte T helper 2 (Th2)-associated pathology, with an allergic inflammatory infiltrate characterized by eosinophils, mast cells, and CD4+ T cells producing interleukin-4 (IL-4), IL-5, and IL-13 in the airways." (PMID 33324573, 2020). "Type 2-high asthma is driven by coordinated GATA3-dependent programs in CD4+ T cells and group 2 innate lymphoid cells (ILC2)." (PMID 42094570, 2026). "Chronic inflammation in asthma typically involves an increase in the number of activated CD4+ T cells, predominantly T helper 2 (Th2) cells." (PMID 41601686, 2026). "T cells, particularly CD4+ T helper cells, play a crucial role in the development and progression of asthma by contributing to airway inflammation, AHR, and tissue remodeling." (PMID 40226621, 2025). "We report a higher frequency of CD62L+ ILC2s and a lower frequency of CD4+ KLRG1+ cells among TCM cells specifically in T2 asthma." (PMID 40965120, 2025). "In asthma, damaged epithelial cells release IL-33, which stimulates Th2 cells by way of Th2 inflammatory cytokines from CD4+T cells." (PMID 40433386, 2025). "In asthma patients, eosinophils and CD4+ lymphocytes that secrete IL-5 are often detected in blood samples and fluid from lung lavage procedures." (PMID 40558541, 2025). "Our results correlate well with studies on asthma cohorts which have highlighted that type 2 and type 17 fungal specific CD4+ T cells are prominent in severe fungal asthma patients." (PMID 39843887, 2025). "The results of quantitative real-time polymerase chain reaction (qRT-PCR) and western blot showed that miR-192-5p expression was decreased, while SCD1 expression was increased in CD4+T cells isolated from the peripheral blood of children with asthma." (PMID 39867638, 2025). "The immune response in asthma is primarily driven by CD4+T helper (Th) cells, which are represented by Th1, Th2, and Th17 cells, particularly Th2 cells." (PMID 39867638, 2025). "plasma cells, T cell CD4 naive, T cell gamma delta, monocytes, macrophages M0, activated dendritic cells and Neutrophils were differential between healthy controls and asthma patients." (PMID 39963184, 2025). "This response is impaired in asthma: CD4+ T cells isolated from the PBMCs of patients with asthma have impaired production of IL-10 in response to CD3/CD46 stimulation compared with controls." (PMID 40309766, 2025).
asthma (continued). "Single-cell sequencing studies in adult asthma have focused on adaptive immunity and reveal that CD4+ T cells constitute the dominant population among PBMCs, exhibiting pro-inflammatory characteristics." (PMID 41550933, 2025). "Recently, Th17 cells, such as CD4+ T cells, have been shown to regulate the involvement of neutrophils in airway inflammation and airway reconstruction in asthma." (PMID 39858200, 2025). "Other studies show that acupuncture and moxibustion can alleviate allergic airway inflammation by regulating the balance of CD4+ T-lymphocyte subtypes in experimental asthma mice." (PMID 40417009, 2025). "It is well-known that dysregulated type 2 (T2) immune inflammation is pivotal in the development of both AD and asthma, traditionally attributed to CD4+ type 2 helper T (Th2) cells." (PMID 40236701, 2025). "In chronic obstructive pulmonary disease (COPD), asthma, and infectious lung diseases, the interaction between CD4+T cells and epithelial cells play a critical role, with distinct mechanisms and manifestations observed across these conditions." (PMID 40433386, 2025). "Although CD4+ Th2 cells undoubtedly play an important role in the pathogenesis of AD and asthma, the discovery of ILC2s has added another layer of complexity to the pathogenesis of these diseases." (PMID 40236701, 2025). "In conclusion, the study suggests that ATR skews CD4+ T cell activation towards Th2, a phenotype that may promote reduced immunosurveillance and increased risk of cancer, as well as Th2-related diseases such as asthma, thereby presenting an environmental and occupation-related risk to human health." (PMID 40025135, 2025). "The frequency of CD62L+ ILC2s was higher and CD4+ KLRG1+ central memory T cells was lower specifically in T2 asthma." (PMID 40965120, 2025). "T cell subsets, particularly CD4+ helper T cells such as Th17 cells, play a central role in mediating the inflammatory response in asthma." (PMID 40226621, 2025). "This suggests that PARP1 helps balance CD4 T cell and T follicular helper cell functions, potentially influencing asthma modulation." (PMID 40634444, 2025). "We found that ICTs (CD24 on IgD+ CD38br and CD3 on CD28+ CD4+) influence asthma through two pathways, mediated by PMs (S‐methylcysteine sulfoxide levels and 1‐myristoyl‐2‐arachidonoyl‐GPC (14:0/20:4) levels)." (PMID 40551049, 2025). "In the type-2 low asthma model, we observed a higher number of neutrophils (p < 0.0001), dendritic cells (DC) (p < 0.0001), and CD4 + T cells (p < 0.05) in Sema3E KO mice compared to WT mice." (PMID 40512736, 2025). "For example, Palikhe and colleagues report that the expression of GATA3 in CD4+ T cells is much higher in severe asthma patients than in those with mild asthma." (PMID 40391221, 2025). "To investigate the effect of shikonin on T-cell populations in asthma mice, we evaluated the phenotypes of CD4+ cells in lung tissues by analyzing the expression of IFN-γ, FOXP3, IL-4, and IL-17 via flow cytometry." (PMID 39444792, 2024). "Overall, this study revealed a unique role of CD226 in CD4+ T cell regulation in asthma pathogenesis." (PMID 39349422, 2024). "We wanted to confirm this mechanism in circulating CD4+ T cells from men and women with severe asthma using a single-cell metabolic approach, SCENITH." (PMID 39404231, 2024). "On the other hand, in experimental studies, CD4+ Th2 cells from a mouse asthma model induced by OVA challenge showed an up-regulation in both miR-23b and miR-27b expression and a downregulation in both miR-106b and miR-203 in naïve CD4+ T cells." (PMID 38337625, 2024). "Although CD4+ T cells (Th17 cells) secreting IL-17 are thought to be the primary source of IL-17 in asthma, cellular sources such as invariant natural killer T (iNKT) and mucosal-associated invariant T (MAIT) cells also produce IL-17." (PMID 39734354, 2024).
asthma (continued). "The cell surface adhesion receptor cluster of differentiation 44 (CD44) as a highly glycosylated molecule, interacted with hyaluronic acid (HA), to participate in the airway accumulation of CD4+ T cells in murine model of asthma." (PMID 38500102, 2024). "Conversely, the adoptive transfer of Th2-polarized CD4+ T cells from mice expressing an OVA-specific T cell receptor (TCR) can induce asthma-like features, further demonstrating the pivotal role of Th2 cells in disease development." (PMID 39664985, 2024). "CD4+ TRMs have been proven to be critical factors in the pathogenesis of asthma through the secretion of Th2 cytokines." (PMID 39632661, 2024). "After the allergic response was induced, the number of CD4+ TRMs was significantly greater in the RSV-infected asthma group than in the other groups." (PMID 39632661, 2024). "On the other hand, PLZF is essential for CD4+ T-cell development and can regulate the memory phenotype of CD44+ CD4+ T cells to promote the development of asthma tolerance." (PMID 39632661, 2024). "A previous study from our group showed that patients with asthma had increased numbers of CD4+ effector T cells and increased expression of metabolic enzymes in their CD4+ T cells compared with those of people in the healthy control group." (PMID 39404231, 2024). "Gain-of-function experiments were performed in mice and human CD4 + T cells to verify the role of c-CBL in asthma and Th2 development." (PMID 39342146, 2024). "Our analysis revealed that treatment with biologics induced changes in subsets of CMs and CD4+ T cells, which suggests the importance of these cell types in the pathogenesis of severe asthma." (PMID 39672815, 2024). "CD4+ T cells are known to play an important regulatory role in asthma development by orchestrating the actions of a variety of effector cells." (PMID 38255279, 2024). "Despite receiving high-dose corticosteroid treatment, CD4+ T cells with IFN-γ+ (TH1 cells) were higher in the BALF of patients with severe asthma than in that of patients with mild or moderate asthma." (PMID 39439788, 2024). "Asthma is an inflammatory disease of the airways mediated by CD4+ T helper (Th) cells that include Th1, Th2, and Th17 cells." (PMID 38378549, 2024). "In the present study, we found that c-CBL was lowly expressed in CD4 + T cells from peripheral blood from asthma children and OVA-challenged neonatal mice." (PMID 39342146, 2024). "Taken together, these findings suggest that the number of CD4+CD44+ memory T cells in lung tissue is highly positively correlated with the severe allergic symptoms of asthma induced by RSV infection, indicating a pulmonary-specific immune response." (PMID 39632661, 2024). "Subsequently, experimental asthma was induced by OVA challenge in neonatal mice, and c-CBL was also downregulated in CD4 + T cells isolated from peripheral blood and spleen from asthma mice." (PMID 39342146, 2024). "In asthma, dendritic cells present antigens to CD4 + T cells by expressing MHC class II molecules and rely on co-stimulatory molecules such as CD40, CD80, CD86 to induce T cell activation." (PMID 38664707, 2024). "IL‐22 is released by several immune cells such as CD4+ T helper cells, γδT cells, NK cells and ILC3 cells and is implicated in the pathophysiology of various chronic inflammatory diseases including asthma and COPD and in mucosal‐associated infections." (PMID 39073027, 2024). "In one article, hsa_circ_0002594 was found to be upregulated within CD4+ T cells from a present microarray dataset containing five asthma patients and five normal subjects." (PMID 39239069, 2024). "The current study found that miR‐1470 expression levels in exosomes of mesenchymal stem cells (MSCs) increased the proportion of CD4+CD25+FOXP3+ cells in asthma patients." (PMID 38545812, 2024).
asthma (continued). "For validation, another cohort including 83 asthma patients and 54 normal controls was analyzed, revealing that hsa_circ_0002594 expression was significantly upregulated in CD4+ T cells from asthma patients." (PMID 39239069, 2024). "In our study, the peripheral blood was collected from childhood asthma cases and healthy children, and the CD4 + lymphocytes (T helper cells) were isolated by magnetic bead sorting." (PMID 39342146, 2024). "We expected the profile of CD4+ T cells, which drive type 2 inflammation in asthma, to be modified with anti-T2 biologics." (PMID 39672815, 2024). "However, whether CD4+ TRMs are protective or pathogenic in RSV-related asthma is still unknown." (PMID 39632661, 2024). "Taken together, these findings indicate that AEC‐Exos promote the enhanced Th2 inflammation by delivering hsa‐miR‐155‐5p to the effector CD4+ T cells in acute asthma exacerbation." (PMID 38938285, 2024). "With increasing resting time, the persistent influence of RSV infection on the pathogenesis of asthma is closely related to CD4+ TRMs." (PMID 39632661, 2024). "PLZF can affect immune tolerance in asthma by regulating immune memory phenotypes, including CD4+ TEMs and CD4+ TCMs." (PMID 39632661, 2024). "Research findings using rat models of asthma demonstrated that the presence of Notch1 and Notch2 on CD4+ T cells, along with Jagged1 on dendritic cells and/or Dll1 on smooth muscle cells, facilitated asthma development." (PMID 39450276, 2024). "After an initial episode of allergen-induced asthma in an experimental murine model, memory CD4+ T cells also persist in the lung despite the administration of FTY720." (PMID 39273153, 2024). "Asthma‐related lung inflammation is mediated by CD4+ T cells, and asthma development is facilitated by enhanced T cell differentiation of Th2 cells." (PMID 38270295, 2024). "Asthma is an inflammatory disease with an abnormal immune response, which is closely related to the activation of CD4+ T helper (Th) cells in the lung." (PMID 39444792, 2024). "The significant differential gene enrichment in CD4+ T cells in pathways such as asthma and inflammatory bowel disease is consistent with some clinical symptoms of DOCK8‐deficient patients, suggesting that the DOCK8 mutation is related to these diseases." (PMID 39329018, 2024). "A study revealed that in an ovalbumin (OVA)-induced asthma model, cDC1-induced CD4+ T cells secreted significantly more IL-4, IL-6, and IL-10, whereas cDC1-induced higher frequencies of IFN-γ and IL-17A production by CD4+ T cells." (PMID 39530090, 2024). "It is generally believed that an increase in CD4+ cells promotes asthma-related cytokines, resulting in bronchial inflammation and other symptoms, but CD8+ cells act oppositely." (PMID 38674852, 2024). "In experimental ovalbumin (OVA)-induced asthma models, genetic or antibody-mediated depletion of CD4+ T cells has been shown to abolish key features of asthma." (PMID 39664985, 2024). "For eosinophils and neutrophils, CD4+ T cells are also key for definition of specific asthma (i.e., T2high vs. T2low asthma) and COPD (e.g., eosinophilic COPD) endotypes." (PMID 39409176, 2024). "High circulating MAIT cells are highly correlated with IFN-γ-producing CD4+ T cells and were suggested to be protective against asthma development." (PMID 39734354, 2024). "Specially, hsa‐miR‐155‐5p is transferred from AEC‐Exos to CD4+ T cells that further induce the enhanced Th2 inflammation during acute asthma exacerbation." (PMID 38938285, 2024). "Type 2 inflammation is the center of asthma development, and mainly mediated by a subset of CD4 + T cells, T helper 2 (Th2) cells." (PMID 39342146, 2024). "The results revealed that the c-CBL expression was significantly reduced in CD4 + T cells from both peripheral blood and spleen of asthma mice, which was consistent with results from asthmatic children." (PMID 39342146, 2024).
asthma (continued). "CD4+ T cells were isolated from PBMCs of 15 patients with asthma (mean age: 43.3 years; 7 females) and 15 healthy controls (mean age: 36.2 years; 7 females)." (PMID 39349422, 2024). "Here, we utilized cKO mice to better understand the role of PLZF in RSV-infected asthmatic mice and the regulatory role of PLZF in CD4+ TRMs, which is closely related to Th2 responses in asthma." (PMID 39632661, 2024). "Foxp3+CD25+CD4+ regulatory T (Treg) cells have been discovered as another pivotal CD4+ T cell subset involved in the pathogenesis of asthma." (PMID 39598682, 2024). "Hsa_circ_0002594 expression in CD4+ T cells of asthma patients was positively related to FeNO, but negatively correlated with PD20 (the methacholine dosage necessary for inducing FEV1 decline by 20%)." (PMID 39239069, 2024). "Previous studies have revealed that there are distinct endotypes of asthma focused on the CD4+ T-cell responses, classified as type 2 (T2)-high endotype vs. non-T2 or T2-low asthma." (PMID 38534377, 2024). "In children with asthma, both CD4+CD25hi Tregs and Foxp3 mRNA expression decrease in the peripheral blood and bronchoalveolar lavage fluid (BALF); this phenomenon can be reversed following treatment with inhaled glucocorticoids." (PMID 39439788, 2024). "Our results revealed that the expression of CD226 was significantly increased in CD4+ effector T cells, especially in T helper (Th) 2 cells and Th17 cells in patients with asthma." (PMID 39349422, 2024). "As shown inFigure 6A,B, the number of pulmonary PLZF+CD4+ TRMs in RSV-infected asthmatic mice was much greater than that in asthmatic mice, suggesting that PLZF likely regulated CD4+ TRMs in asthma exacerbation." (PMID 39632661, 2024). "Type 2 airway inflammation (T2AI), driven by type 2 innate lymphoid and CD4+ T helper 2 cells, leads to various diseases and conditions, such as chronic rhinosinusitis with nasal polyps, allergic rhinitis, and asthma." (PMID 39273399, 2024). "Our findings revealed that CD4+ TRMs were more highly expressed in the lungs of RSV-infected asthma model mice than in those of circulating CD4+ memory T cells, including CD4+ TEMs and CD4+ TCMs, for at least 6 weeks in BALB/c mice." (PMID 39632661, 2024). "RNA sequencing (RNA-Seq) was carried out on peripheral blood CD4+ T cells and thousands of differentially expressed genes were identified in both asthma groups compared to heathy controls." (PMID 38255279, 2024). "To further elucidate the regulatory effect of PLZF on CD4+ TRMs in RSV-infected asthma, we successfully knocked outZbtb16 in CD4+ T cells, namely, Zbtb16flox/flox CD4Cre (cKO)." (PMID 39632661, 2024). "In a separate study, the authors identified another circRNA, hsa_circ_0002594, which exhibited upregulation in CD4+ T cells using the existing micro-array dataset consisting of 5 patients with asthma and 5 healthy controls." (PMID 38078005, 2023). "The identification of a CD4+ T-cell master regulator provides an important step towards the discovery of new druggable targets and possible biomarkers for asthma diagnosis." (PMID 38129444, 2023). "A study of patients with severe asthma showed that both miR-146a and miR-146b were decreased in CD4+ T and CD8+ T cells." (PMID 36865391, 2023). "Some studies have shown that TC2 cells are more strongly associated with corticosteroid insensitivity, persistent airway eosinophilia, severe asthma, and atopic asthma than CD4+ TH2 cells." (PMID 37415598, 2023). "Meanwhile, the box plot results indicated that the number of memory B cells, CD8 + T cells, naive CD4 + T cells, and M0 macrophages significantly differed between patients with asthma and normal groups." (PMID 37259023, 2023). "The expressions of lncRNA-MEG3 and 18 other lncRNAs were significantly changed in CD8+ T cells of patients with severe asthma, and 5 lncRNAs were differentially expressed in CD4+ T cells." (PMID 36865391, 2023).